NFILZ (NFIL3 like basic leucine zipper)
Synonyms: LINC01862
Gene: Protein-coding gene on chromosome 19 (8,630,633 to 8,681,151, forward strand). Ensembl gene ENSG00000268480.
Subcellular location: Nucleus
Gene Ontology:
Molecular function: DNA binding; DNA-binding transcription factor activity
Biological process: circadian rhythm; regulation of DNA-templated transcription
Cellular component: nucleus
Homologues: Orthologues: macaque NFILZ (94% identical), dog NFILZ (73% identical), pig NFILZ (72% identical), rat Nfilz (57% identical), mouse Nfilz (57% identical), zebrafish nfil3-4 (25% identical), Drosophila melanogaster vri (21% identical), zebrafish si:dkey-172o19.2 (19% identical), Caenorhabditis elegans atf-2 (17% identical). Paralogues in human: NFIL3 (26% identical).